IL6 (interleukin 6)
Diseases named in the same sentence as IL6 in open-access papers (continued):
Sharing a sentence is not in itself a finding about the gene and the disease.
tumor (continued). "We found that IL-6 levels in CAF-derived CM were approximately 3.5-fold higher than in tumor cell-derived CM, indicating that IL-6 was predominantly secreted by CAFs." (PMID 40718440, 2025). "Inside the TIME in esophageal cancer, CAFs release the proinflammatory cytokine interleukin‐6 (IL‐6), which increases the frequency of Foxp3+ tumor‐infiltrating lymphocytes (TILs) and impairs the CD8+ T‐cell response." (PMID 41346571, 2025). "In terms of inflammation regulation, taurine inhibits the NF-κB pathway to reduce the secretion of pro-inflammatory cytokines such as IL-6 and IL-8, thereby suppressing tumor cell proliferation and angiogenesis." (PMID 40630945, 2025). "Persistent expression of inflammatory factors produced within the tumor microenvironment, including GM-CSF, G-CSF, IL-6, IL-1β, TNF-α, and IFN-γ, is known to promote the expansion of immunosuppressive cells." (PMID 40822347, 2025). "We propose to restore the function of exhausted CD8+ T cells in the tumor microenvironment by combined blockade of PD1 and IL-6 thereby inhibiting tumor growth." (PMID 40040705, 2025). "Interleukin-6 (IL-6) and IL-8 promote tumor angiogenesis and metastasis by activating the STAT3 and NF-κB pathways." (PMID 40823082, 2025). "IL-1β suppresses anti-tumor immune responses by promoting Tregs, IL-6 promotes tumor growth and metastasis while inhibiting anti-tumor immunity, and IFN-γ activates CD8+ cytotoxic T lymphocytes, enhancing their tumor-killing ability." (PMID 39955603, 2025). "Through a variety of downstream mediators, IL-6 exerts an intrinsic effect on tumor cells that promotes cancer cell survival, proliferation, and metastasis." (PMID 40933989, 2025). "The cytokine IL-35 has been demonstrated to promote N2 neutrophil polarization by upregulating the expression of G-CSF and IL-6, consequently enhancing neutrophil recruitment and infiltration into the tumor microenvironment." (PMID 41254689, 2025). "On the contrary, IL-6 exhibits pro-tumor properties by influencing the survival, proliferation, and metastatic potential of tumor cells." (PMID 41376623, 2025). "Previous studies have demonstrated that Fib can activate monocytes to secrete proinflammatory cytokines such as tumor necrosis factor-α (TNF-α) and IL-6, thereby promoting tumor cell proliferation and survival." (PMID 41426339, 2025). "To further investigate this finding, we conducted silencing experiments on PTPN23, which revealed its functional role in promoting tumor growth, potentially mediated through the IL-6/JAK/STAT3 signaling pathway." (PMID 40570022, 2025). "Recent studies have elucidated molecular mechanisms regulating IL-6 secretion by CAFs, contributing to chemoresistance and tumor progression." (PMID 40718440, 2025). "Among them, interleukins like IL-6, IL-8, and IL-10 play prominent roles in shaping tumor behavior and immune cell activity." (PMID 40563651, 2025). "When their levels drop, inflammation increases through higher activity of signaling molecules like IL-6, which again encourages tumor development." (PMID 41514860, 2025). "Significant evidence suggests that cytokines and glucocorticoids are linked to a poorer prognosis in cancer patients.IL-6 and TNF-α play roles in all stages of tumor development, including formation, progression, and metastasis." (PMID 40098072, 2025). "STAT3 activation in neutrophils enhances their production of pro-inflammatory cytokines (such as IL-6 and IL-8) and other mediators (e.g., MMPs), which support the tumor’s inflammatory milieu." (PMID 40486614, 2025). "In the tumor microenvironment, particularly in prostate cancer, YY1 is enriched in M2-like macrophages and promotes IL-6 expression, contributing to tumor progression." (PMID 41459495, 2025). "Itis important to note that IFN-γ- or TNF-α-induced ferroptosis candevelop only at the initial stages of the disease; when the tumor switches tothe aggressive growth phase, a shift towards IL-6 secretion occurs." (PMID 40264585, 2025).
tumor (continued). "TNBC demonstrates significantly heightened immunogenicity compared to ER-positive/HER2-negative BC, owing to its enriched tumor microenvironment characterized by elevated TILs, pro-inflammatory mediators (e.g. IL-6, CXCL10), and CD8+T cells." (PMID 40438111, 2025). "Previous studies have shown that tumor-associated macrophages can secrete inflammatory cytokines such as TNF-α and IL-6, activating the STAT3 signaling pathway and thereby promoting chemotherapy resistance in OS cells." (PMID 41285805, 2025). "Activation of TIM-3 leads to immune exhaustion of CD8+ T cells and can induce macrophage polarization towards the M2 type, thereby promoting tumor growth through increased secretion of interleukin-6 (IL-6)." (PMID 39915447, 2025). "In the context of colitis-associated cancer (CAC), neutrophil-derived IL-1β stimulates intestinal mononuclear phagocytes (MPs) to produce IL-6, thereby promoting tumor growth." (PMID 41267807, 2025). "iCAFs, which have low α-smooth muscle actin (αSMA) expression, are found scattered throughout the tumor mesenchyme and often located near to the blood vessels, producing high amounts of inflammatory cytokines, such as IL-6." (PMID 40248695, 2025). "Pro-inflammatory cytokines such as TNF-α and IL-6, regulated by NF-κB, enhance PD-L1 expression, enabling tumor cells to interact with the programmed death-1 (PD-1) receptor on T-cells." (PMID 39949765, 2025). "After intradermal administration, the micelles promoted secretion of pro‐inflammatory cytokines (i.e., IFN‐γ, TNF‐α, IL‐4, IL‐6, IL‐12) and increased tumor infiltration of CD4+ and CD8+ T cells for robust antitumor immune responses." (PMID 41287898, 2025). "Previous studies have established that the expression of CD274/PD-L1 was associated with multiple signaling pathways, including IL-6/JAK/STAT3, PI-3K/AKT/mTOR, JAK/STAT, and WNT, which collectively influenced the tumor immune microenvironment." (PMID 40953006, 2025). "Despite promising findings, resistance to BET-targeted therapies have been observed, particularly in TNBC, where TAMs sustain tumor growth through IL-6/IL-10–driven STAT3/NF-κB signaling." (PMID 41583469, 2025). "Since IL-1β, IL-6, and TNF-α are well-established mediators of tumor-associated inflammation, their downregulation is mechanistically relevant." (PMID 41470183, 2025). "Studies have shown that exercise can slow tumor metastasis by reducing the levels of proinflammatory factors, such as IL-6 and TNF-α." (PMID 40370453, 2025). "IL-6, a pleiotropic pro-inflammatory cytokine, plays a key role in tumor-promoting inflammation, tumorigenesis, and immune modulation in somatic mutant tumor cells." (PMID 41184283, 2025). "The convergence of these pathways means that when both TGFB2 and IL6 are upregulated, their cooperative effects on the tumor stroma and the immune system are accentuated, rendering them particularly predictive of poor outcomes in PDAC." (PMID 40650134, 2025). "Altogether, our study identified a mechanism by which tumours, through Upd3 or IL-6 signalling, induce hepatic gluconeogenesis independently of the Cori cycle, highlighting a direct influence of tumour-derived factors on hepatic glucose metabolism." (PMID 40275022, 2025). "TMEs linked to NEPC also contain a large number of immune and stromal cells, which release cytokines, such as interleukin-6 (IL-6), that promote tumor growth and metastasis." (PMID 41573638, 2025). "IL6 plays a key role in senescence induction and tumor promotion by regulating myeloid-derived suppressor cells (MDSCs), which suppress T-cell-mediated antitumor immunity." (PMID 40312750, 2025). "Peritumoral endothelial cells isolated from HCC patients show greater proliferative capacity in response to IL-6 and soluble IL-6R stimulation compared to endothelial cells from tumor tissue." (PMID 40918452, 2025).
tumor (continued). "Leronlimab reduced circulating tumor-associated cells and modulated CCR5-related cytokine production (CCL5, IL-6, and TNF-α), highlighting the potential of CCR5 blockade to reprogram the immunosuppressive microenvironment." (PMID 40868199, 2025). "On the contrary, various chemical mediators released by TAMCs, such as TNF-α, IL-1, IL-6, tryptase, chondroitin, and sulfate, trigger antitumor immune responses, including inflammation leading to apoptosis in the tumor." (PMID 40805183, 2025). "IL-6 is known for its ability to enhance tumor invasion and angiogenesis while mediating communication between tumor cells and immune cells, such as tumor-associated macrophages, which can increase tumor aggressiveness." (PMID 40433410, 2025). "Tumor-associated OC endothelial cells within the OC-TME exhibit increased expression of IL6 receptor (IL6R), and upon activation by IL6, they induce the expression of vascular endothelial growth factor (VEGF), which drives angiogenesis." (PMID 40427188, 2025). "CAFs remodel the extracellular matrix (ECM) by secreting cytokines such as FGF and IL-6, as well as growth factors, thereby enhancing tumor invasiveness and metastatic potential." (PMID 40746533, 2025). "Whereas, in another experiment, the mangiferin encapsulated AuNPs on PC-3 cells reduced the IL-6 and IL-10 (pro-tumor) and increased the TNF-α and IL-12 expression in the treated groups." (PMID 40712409, 2025). "Tumor-derived IL-6 promotes the formation of inflammatory CAFs via the JAK/STAT pathway through co-culture of tumor organoids and CAFs." (PMID 39891284, 2025). "IL-6 is a common cytokine and a major mediator of inflammation, predominantly released by stromal cells, immune cells, and tumor cells in the tumor microenvironment." (PMID 40433391, 2025). "Under stimulation from liver surgery or CXCL6 derived from metastatic tumor cells, the IL‐6/STAT3/SAA signaling pathway in hepatocytes is activated, promoting MDSCs infiltration, NETs generation, and macrophage M2 polarization." (PMID 40027151, 2025). "Cytokines including IL-6, IL-10, IL-11 and IL-24 can suppress immune effector cells, such as T cells, natural killer cells and dendritic cells, impairing the host’s anti-tumour response while facilitating the immune evasion of GBM cells." (PMID 41301734, 2025). "Our results found that IL-6 significantly increased the cytotoxicity of CIK cells, however, previous studies demonstrated that tumor-derived IL-6 and IL-8 impair the anti-tumor activity of NK cells." (PMID 40369131, 2025). "IL6 inhibition can also suppress B-cell activation and antibody production, further decreasing tumor-promoting effects driven by IL6." (PMID 40427188, 2025). "IL-6, a pro-inflammatory cytokine, serves a dual function by supporting both inflammation and tumor progression." (PMID 39949765, 2025). "Serial serum CA19-9, CA-125 and IL-6 levels tracked closely with radiologic tumour burden, underscoring the value of these markers as indicators of disease activity." (PMID 41476977, 2025). "IL-6 is highly expressed in the serum of EC patients, and the expression level of IL-6 in the serum significantly increases with the increase of tumor stage." (PMID 40606986, 2025). "IL-6 and TNF-α, which are closely associated with chronic inflammation, are significantly reduced by exercise, alleviating inflammation in the tumor microenvironment." (PMID 40370453, 2025). "In the reported breast cancer study using an orthotopic tumor model, the authors demonstrated that IL-6 and IL-4 secretion by these stromal cells facilitates tumor progression and immune modulation." (PMID 40453074, 2025). "Tumor-associated fibroblasts secrete cytokines such as TGF-β and IL-6, reinforcing EMT signaling and supporting tumor progression." (PMID 40277909, 2025).
tumor (continued). "The focus of this previous study, however, was on the immunomodulatory effect of cisplatin in MSCs, specifically the suppression of IL-6 and IDO1 and the associated potential effects on the tumor microenvironment." (PMID 41515960, 2025). "Sustained IL-6 elevation promotes malignant cell immune evasion by modifying the tumor microenvironment." (PMID 41019062, 2025). "IL-6 upregulates immunosuppressive cells, inhibits anti-tumor immune cells, or reduces their infiltration, constructing a highly immunosuppressive tumor microenvironment, potentially leading to ESCC progression and treatment resistance." (PMID 40433391, 2025). "Research indicates IL-6 plays a critical role in tumorigenesis by promoting tumor cell proliferation, immune evasion, survival, angiogenesis, and metastasis." (PMID 40443668, 2025). "CAFs enhance tumor progression by remodeling the extracellular matrix and secreting cytokines like IL-6, creating a supportive niche." (PMID 39956902, 2025). "MSCs can be reprogrammed by gastric cancer to promote tumor growth and immunosuppression, as well as enhance angiogenesis via IL-6 secretion." (PMID 40872551, 2025). "The analysis revealed activation of the inflammatory response and the IL6–JAK–STAT3 signaling pathways in tumor cells with high LCN2 expression." (PMID 41436606, 2025). "Recent research has demonstrated that lactate drives macrophage remodeling by inhibiting RARγ expression, enhancing interleukin-6 levels in the tumor microenvironment, and activating the STAT3 signaling pathway to promote CRC progression." (PMID 40900785, 2025). "N1 neutrophils inhibit proliferation and release high levels of TNF-α, whereas N2 neutrophils, which have a longer lifespan, support cancer growth by producing pro-tumor factors like ROS, neutrophil extracellular traps (NETs), IL-6, IL-8, and MMP-9." (PMID 40636453, 2025). "Disruption of IL-6 signaling delays tumor development in a murine inflammation model, suggesting the role of IL-6 not only in initiation, but also during neoplastic transformation." (PMID 41376623, 2025). "IL-6 expressed at high level in the tumor microenvironment promotes tumor cell proliferation, survival, invasion and metastasis." (PMID 40255422, 2025). "The consistent demonstration of IL-10/IL-6 imbalance in both the peripheral circulation (serum) and tumor microenvironment (RNA-seq) underscores the biological significance of this cytokine axis in DLBCL pathogenesis." (PMID 40881684, 2025). "It is also possible that donor IL6 affects both relapse and extensive cGVHD by changing the counteracting balance between the graft-versus-tumor and the graft-versus-host effects." (PMID 39860482, 2025). "Among M1 and M2 macrophages, M1 macrophages are proinflammatory; they produce proinflammatory factors such as IL-6 and IL-12 and promote tumor necrosis-α expression." (PMID 40191205, 2025). "In parallel, adipokines such as leptin and interleukin-6, upregulated under hypoxic conditions, promote tumor progression and facilitate immune evasion." (PMID 41323785, 2025). "To investigate the relationship between IL-6 and tumor cell proliferation in NSCLC, we found that IL-6 was positively correlated with a series of tumor-associated pathways by TCGA." (PMID 40040705, 2025). "Cytokines like IL-6, G-CSF, and M-CSF not only influence tumor metastasis and angiogenesis, but also regulate bone marrow cell function and platelet size, underscoring PDW's potential as a cancer outcome indicator." (PMID 40224488, 2025). "IL6 influences all three “E” phases of immunoediting, playing a key role in modulating the tumor’s immunophenotype, i.e., “hot” and “cold”." (PMID 40427188, 2025). "In the Tumor–Myeloid interaction, enrichment was observed in immune-related pathways such as ‘IL-6/JAK/STAT3 Signaling’, ‘Cytokine–cytokine receptor interaction’, ‘Inflammatory Response’, and ‘Chemokine binding’." (PMID 40806243, 2025).
tumor (continued). "Western Blotting revealed higher IL6 expression in the infiltrated adipose tissue around the tumor in HFD mouse compared to the contralateral adipose tissue of the tumor." (PMID 40841364, 2025). "When combined with anti-PD-1 therapy, ES@CuO significantly increased tumor-infiltrating lymphocytes and upregulated key cytokines (IL-6, TNF-α, IFN-γ), confirming its ability to reprogram the immunosuppressive tumor microenvironment via cuproptosis." (PMID 40791799, 2025). "The main function of these immune cells is to secrete a large number of inflammatory factors, such as IL-1 and IL-6, to induce an inflammatory response, which also plays a dual role in the regulation of tumor processes." (PMID 40420185, 2025). "All of them can induce tumor growth, cell invasion, and proliferation, with IL–6 also being responsible for angiogenesis." (PMID 40427098, 2025). "AurA deficiency or inhibition decreased IL-6 and TNF production in β-glucan-trained BMDMs upon rechallenge by LPS or supernatant from tumor cells." (PMID 40920087, 2025). "Blocking IL-6 signaling with tocilizumab has shown promise in preclinical cancer models, leading to reduced tumor growth and reversal of immunosuppression." (PMID 41007766, 2025). "The increase in forward scatter median following Pam3CSK4 stimulation suggests heightened neutrophil activity, leading to the secretion of cytokines and chemokines like TNF, IL-6, and IL-8, which promote tumor cell proliferation, invasion, and metastasis." (PMID 39960903, 2025). "Animal studies showed that upregulation of inflammatory cytokine pathways such as Interleukin-6 (IL-6), IL-8, and Tumour Necrosis Factor (TNF)-α is linked to PCa tumour growth." (PMID 40941553, 2025). "In this model, M2-like TAMs significantly promoted tumour cell proliferation and suppressed invasion, implicating IL-6-mediated signalling in driving these tumour behaviours." (PMID 40420192, 2025). "As a result, these TAK1 mutants defected TAK1's oncogenic functions to promote cancer cell proliferation, tumor growth in vivo, and elevate p65 downstream targeted genes such as TNFα, IL‐6 and IL‐1β.." (PMID 40999870, 2025). "Patients treated with RFA exhibit elevated levels of interleukin-6 (IL-6) and local or systemic inflammatory responses, indicating that the inflammatory response significantly contributes to rapid tumor progression following RFA." (PMID 41403696, 2025). "TNF-α promotes tumor cell death by killing T cells or other cells, and IL-1β and IL-6 play important roles in immune response and protein synthesis during the acute phase." (PMID 39857446, 2025). "IL‐6 promotes tumour progression by fostering a pro‐inflammatory microenvironment that supports angiogenesis, tumour cell survival and metastasis." (PMID 41380167, 2025). "The hyperactivated IL6/JAK/STAT3 can facilitate tumor cell proliferation and invasiveness; hence treatments targeting the IL6/JAK/STAT3 pathway are expected to inhibit tumor cell growth." (PMID 41044672, 2025). "This dysfunction is mediated by a pro-inflammatory tumor microenvironment, where cytokines such as IL-1β, IL-6, IFN-γ, and TNF-α activate Toll-like receptors (TLRs), promoting taste bud apoptosis and impairing cellular turnover." (PMID 40868108, 2025). "The glioma microenvironment is enriched with pro-inflammatory cytokines, such as IL-1β, IL-6, and TNF-α, along with tumor-associated macrophages (TAMs) and microglia." (PMID 40881678, 2025). "In a previous study, it was confirmed that the activity of NK cells in HCC expressing HIF-1α by treatment with CoCl2 was increased due to the blocking of IL-6 in the tumor microenvironment (TME)." (PMID 40430040, 2025). "IL-11 is a pleiotropic cytokine belonging to the IL-6-related cytokine family that has recently emerged as a tumor-promoting biomarker." (PMID 40426949, 2025). "This correlation is primarily linked to the activation of the IL-6/STAT3 signaling pathway, which plays a crucial role in tumor progression and prognosis in CRC." (PMID 41007818, 2025).